RDH10 (retinol dehydrogenase 10)
Description:
Retinol dehydrogenase with a clear preference for NADP. Converts all-trans-retinol to all-trans-retinal. Has no detectable activity towards 11-cis-retinol, 9-cis-retinol and 13-cis-retinol.
Synonyms: SDR16C4
Tractability: Antibody: UniProt predicts a signal peptide or a membrane-spanning region. PROTAC: ubiquitination databases record sites on it; its protein half-life has been measured.
Gene: Protein-coding gene on chromosome 8 (73,294,602 to 73,325,281, forward strand). Ensembl gene ENSG00000121039.
Subcellular location: Microsome membrane; Endoplasmic reticulum membrane
Subcellular location (Human Protein Atlas): Lipid droplets
Pathways (Reactome):
Sensory Perception: The canonical retinoid cycle in rods (twilight vision)
Signal Transduction: RA biosynthesis pathway
Gene Ontology:
Molecular function: all-trans-retinol dehydrogenase (NAD+) activity; protein binding; all-trans-retinol dehydrogenase (NADP+) activity; oxidoreductase activity, acting on the CH-OH group of donors, NAD or NADP as acceptor
Biological process: retinal metabolic process; retinol metabolic process; visual perception; retinoid metabolic process; positive regulation of retinoic acid biosynthetic process; regulation of hormone levels
Cellular component: cytoplasm; lipid droplet; membrane; nucleus; endoplasmic reticulum membrane
Genetic constraint (gnomAD): Loss-of-function variants: 12 observed, 20.14 expected, observed/expected ratio (o/e) 0.6, 90% interval 0.38 to 0.96. The synonymous counts are far from expectation, so gnomAD's model fits this gene poorly and the ratio says little. Missense variants: 237 observed, 337.87 expected, observed/expected ratio (o/e) 0.7, 90% interval 0.63 to 0.78. Synonymous variants: 167 observed, 132.94 expected, observed/expected ratio (o/e) 1.26, 90% interval 1.11 to 1.43.
Homologues: Orthologues: chimpanzee RDH10 (100% identical), macaque RDH10 (100% identical), rabbit RDH10 (100% identical), rat Rdh10 (99% identical), mouse Rdh10 (99% identical), dog RDH10 (96% identical), tropical clawed frog rdh10 (89% identical), zebrafish rdh10a (79% identical), pig RDH10 (77% identical), zebrafish rdh10b (76% identical). Paralogues in human: SDR16C5 (40% identical), HSD17B11 (36% identical), HSD17B13 (36% identical), DHRS3 (33% identical), HSD17B6 (23% identical), RDH5 (22% identical), DHRS9 (21% identical), SDR9C7 (21% identical), RDH16 (21% identical), HSD17B2 (20% identical), HSD17B4 (20% identical), RDH11 (19% identical), and 13 more.
Diseases named in the same sentence as RDH10 in open-access papers:
RDH10 is named in the same sentence as 40 diseases in open-access papers, as found by Europe PMC text mining. Sharing a sentence is not in itself a finding about the gene and the disease. The quoted sentences say what the papers report.
type 2 diabetes mellitus (4 papers, 2019 to 2025). A type of diabetes mellitus that is characterized by insulin resistance or desensitization and increased blood glucose levels. "In this study, we demonstrated that in type 2 diabetes mellitus (T2DM), impaired cardiac retinol metabolism caused by cardiac RDH10 reduction results in DCM through Rol overload-induced cardiotoxicity and atRA deficiency-induced lipotoxicity and ferroptosis." (PMID 36864033, 2023). "Retinol dehydrogenase 10 (RDH10) metabolism disorder exists in the hearts of mice and the patients with type 2 diabetes mellitus (T2DM)." (PMID 37942067, 2023).
hepatocellular carcinoma (3 papers, 2015 to 2022). A malignant tumor that arises from hepatocytes. "Roles of RDH10 in cancer have been investigated in hepatocellular cancer cell line (HepG2), which showed that RDH10 over-expression inhibited cell growth." (PMID 29285249, 2017). "The mRNA expressions of RALDH1 and RALDH2 were also slightly higher in HCC than in normal livers, and protein expressions of RALDH1, ADH1 and especially RDH10 were also detected in hepatic carcinoma tissues." (PMID 26571119, 2015). "Finally, RDH10 overexpression has an antiproliferative effect on hepatocellular carcinoma cell lines." (PMID 36139698, 2022).
melanoma (3 papers, 2022 to 2024). A malignant, usually aggressive tumor composed of atypical, neoplastic melanocytes. "Treg signature genes CXCR5, TNFRSF9, CCR7, STAT1, GBP4, and EOMES were significantly upregulated in the young cohort and were correlated with higher survival in melanoma, while ID3, IL-17A, IL-17F, RDH10 and IL-11 were significantly upregulated in the old cohort." (PMID 36135194, 2022). "From other validated targets in this study that have not yet been investigated in melanoma, we would like to point out MRAS, IL1R2, RAB34, LAPTM5, RDH10, and STK32C." (PMID 36139698, 2022).
non-small cell lung carcinoma (3 papers, 2015 to 2017). A group of at least three distinct histological types of lung cancer, including non-small cell squamous cell carcinoma, adenocarcinoma, and large cell carcinoma. "Reports of lung cancer showed that RDH10 mutations were common in malignant non-small-cell lung cancer." (PMID 29285249, 2017). "RDH10 was reported to play critical oncogenic roles in tumor progression for patients of non-small-cell lung cancer, and was involved in tumors with lymph node invasion." (PMID 27786176, 2016).
diabetic cardiomyopathy (2 papers, 2023 to 2025). Diabetic cardiomyopathy is a disorder of the heart muscle in people with diabetes. "Therefore, we suggest that the reduction of cardiac retinol dehydrogenase 10 and its mediated disorder of cardiac retinol metabolism is a new mechanism underlying diabetic cardiomyopathy." (PMID 36864033, 2023).
glioma (2 papers, 2017 to 2024). A benign or malignant brain and spinal cord tumor that arises from glial cells (astrocytes, oligodendrocytes, ependymal cells). "As the coefficients of Cox's regression model was positive (B value=1.068), these data suggested that the higher RDH10 level indicated a worse prognosis for glioma patients, and was associated with a 2.908-fold increased risk of death (Exp(B)=2.908)." (PMID 29285249, 2017). "To investigate whether there is a causal relationship between RDH10 expression and development of human glioma, we examined the RDH10 expression in glioma cell lines U87, U251, U373 and A172." (PMID 29285249, 2017). "In addition, high RDH10 expression was associated with malignant progression and poor prognosis in glioma patients, indicating that RDH10 may regulate human glioma development and progression." (PMID 29285249, 2017). "However, it was unclear whether the poor effect of RA treatment in glioma patients was associated with the RDH10 expression." (PMID 29285249, 2017). "After that, we found that 6 immune checkpoints (CD274, CTLA4, LAG3, LGALS9, PDCD1, and PDCD1LG2) were significantly upregulated in the high-glioma-risk group, while RDH5, RDH10 and DHRS3 simultaneously have a substantial positive connection with PDCD1LG2." (PMID 39465792, 2024). "ADH4, DHRS3, LRAT, RDH10, RDH12, and RDH5 were higher expressed in the high-glioma-risk group while DHRS9 was lower expressed." (PMID 39465792, 2024). "Analysis with Cox's regression model revealed that RDH10 expression had independent impact on glioma patients’ survival (B=1.068, ***P < 0.001)." (PMID 29285249, 2017). "In our study, 150 human glioma samples of grades I–IV were harvested to evaluate RDH10 expression by immunohistochemistry (IHC)." (PMID 29285249, 2017). "To investigate the mechanisms of how RDH10 regulates glioma progression, we performed whole-genome expression microarray on U-87 cells expressing either Scr-shRNA or RDH10-shRNA." (PMID 29285249, 2017). "Our results show that RDH10 knockdown inhibits glioma cell proliferation, survival, cell cycle, and invasion." (PMID 29285249, 2017). "Positive RDH10 expression was found in 5/36 grade I glioma specimens, 17/39 grade II specimens, 24/34 grade III specimens, and 37/41 grade IV specimens." (PMID 29285249, 2017). "Persistent proliferation signals are an important marker of cancer; thus, it was important to study the impact of RDH10 knockdown on glioma cell proliferation." (PMID 29285249, 2017). "This is the first report that demonstrates the positive correlation between RDH10 expression and glioma progression and grades." (PMID 29285249, 2017). "In vitro, lentivirus-mediated shRNA knockdown of RDH10 suppressed glioma cell proliferation, survival, and invasiveness and cell cycle progression." (PMID 29285249, 2017). "Analysis of GE-mini dataset demonstrated that the expression of RDH10 is increased in gliomas compared to normal brain tissues, especially in GBM." (PMID 29285249, 2017). "To elucidate the mechanism as to how RDH10 promotes glioma cell proliferation and survival, we performed a whole-genome expression microarray in glioma cells with suppressed RDH10." (PMID 29285249, 2017). "In this study, we have analyzed the RDH10 expression in human gliomas, and investigated the role of TWEAK–NF-κB axis during glioma development." (PMID 29285249, 2017). "Together, our results demonstrate that RDH10 induces survival, proliferation, and invasion of glioma cells, both in vivo and in vitro." (PMID 29285249, 2017). "Gene and protein levels of RDH10 were significantly decreased in cells that received RDH10-shRNA, demonstrating that the lentivirus-based shRNA strategy efficiently inhibited RDH10 expression in glioma cells." (PMID 29285249, 2017). "The volumes of glioma xenografts with suppressed RDH10 were significantly smaller than the control tumors." (PMID 29285249, 2017).
glioma (continued). "Here, we show that RDH10 is highly expressed in human gliomas, and its expression correlates with tumor grade and patient survival times." (PMID 29285249, 2017). "IHC data demonstrated that RDH10 was expressed in glioma specimens of different grades to different degrees." (PMID 29285249, 2017). "Our in vitro data demonstrated that RDH10 suppression inhibited glioma cell survival, proliferation, and invasion ability." (PMID 29285249, 2017). "Together, our results indicate that RDH10 induces glioma development and progression, and suggest that it may serve as a potential novel target for human glioma treatment." (PMID 29285249, 2017). "This suggests that RDH10 promotes glioma cell proliferation and survival by regulating the TWEAK-NF-κB axis, and that it could potentially serve as a novel target for human glioma treatment." (PMID 29285249, 2017). "Our results demonstrate that RDH10 is highly expressed in gliomas and correlates with poor prognosis, suggesting that it may serve as a new target for glioma treatment." (PMID 29285249, 2017). "In vivo, RDH10 knockdown reduced glioma growth in nude mice." (PMID 29285249, 2017). "In this study, we analyzed the biological function of RDH10 in human gliomas." (PMID 29285249, 2017). "Together, these data indicate that the RDH10 expression may serve as a potential biomarker in the pathogenesis and progression of gliomas." (PMID 29285249, 2017). "As both gliomas grade and RDH10 expression had a significant influence on patient survival, we wondered whether RDH10 expression was an independent prognostic factor of glioma patients’ survival." (PMID 29285249, 2017). "The percentage of apoptotic U251 cells also significantly increased following RDH10-shRNA treatment compared with Scr-shRNA (12.04 ± 1.12 % vs 1.67 ± 0.12%, respectively; P = 0.0036), indicating that RDH10 may have an anti-apoptotic role in glioma cells." (PMID 29285249, 2017). "The prognostic signature comprised of ADH4, DHRS3, DHRS9, LRAT, RDH10, RDH12, and RDH5 based on RA metabolism was established, which provided a theoretical basis and reference value for the research of glioma." (PMID 39465792, 2024). "Ultimately, ADH4, DHRS3, DHRS9, LRAT, RDH10, RDH12, and RDH5 were selected as prognostic genes for building an RA metabolism–related prognostic signature with glioma." (PMID 39465792, 2024). "We identified 7 promising prognostic genes (ADH4, DHRS3, DHRS9, LRAT, RDH10, RDH12, and RDH5) within glioma and developed a prognostic model with significant predictive accuracy." (PMID 39465792, 2024). "To date, except for RDH10, no comprehensive studies have established a link between the remaining 6 genes and glioma." (PMID 39465792, 2024).
Glucose intolerance (2 papers, 2021 to 2025). Glucose intolerance (GI) can be defined as dysglycemia that comprises both prediabetes and diabetes. "Elimination of one Rdh10 copy (Rdh10+/−) increased adiposity, hepatic steatosis, glucose intolerance and insulin resistance in male mice fed HFD." (PMID 39925846, 2025). "Relative to wild-type (WT) controls, Rdh10+/− males fed a high-fat diet decrease reliance on fatty-acid oxidation and experience glucose intolerance and insulin resistance." (PMID 34419449, 2021). "The average amount of glucose in fasted male GM decreased by 34%, reflecting the decrease in Glut1 and gluconeogenesis genes and the glucose intolerance and insulin resistance of male Rdh10+/− mice." (PMID 34419449, 2021). "Rdh10+/− females fed this diet increase fatty acid oxidation and experience neither glucose intolerance nor insulin resistance." (PMID 34419449, 2021). "Rdh10+/− males fed a purified HFD from weaning endure glucose intolerance and insulin resistance, but females were not assessed." (PMID 34419449, 2021). "Here we found that Rdh10+/− females of the same age and fed a purified HFD diet with the same formulation since weaning did not experience glucose intolerance or insulin resistance." (PMID 34419449, 2021).
heart failure (2 papers, 2023 to 2025). Inability of the heart to pump blood at an adequate rate to meet tissue metabolic requirements. "Cardiomyocyte-specific RDH10 knockout (RDH10-cKO) mice exhibit halved retinoic acid levels, heart failure, and severe cardiac remodeling, which AAV9-RDH10 injection mitigates." (PMID 39925846, 2025). "Our further results showed that at week 15 after TMX treatment, RDH10-cKO mice exhibited a halving of cardiac atRA, heart failure, and severe cardiac structural remodeling including myocardial hypertrophy, myocardial fibrosis, apoptosis, lipid deposition and increased mitochondria in cardiomyocytes." (PMID 36864033, 2023).
Insulin resistance (2 papers, 2021 to 2025). Increased resistance towards insulin, that is, diminished effectiveness of insulin in reducing blood glucose levels. "We conclude that Rdh10/RA affects whole body energy use and insulin resistance partially through sexual dimorphic effects on skeletal muscle gene expression, structure, and mitochondria activity." (PMID 34419449, 2021).
breast carcinoma (1 paper, 2021). "Furthermore, we generated an expression risk score for each of the breast cancer patients in the METABRIC Discovery, Validation and TCGA sets using the seven genes RDH5, RDH8, RDH10, RDH11, RDH12, RDH13, RDH14." (PMID 33436820, 2021). "To explore the expression patterns of the seven genes RDH5, RDH8, RDH10, RDH11, RDH12, RDH13, RDH14 in normal tissues as well as breast cancer tissue, we first drew a heat map of the expression levels of the genes across normal human tissues from GTEx portal." (PMID 33436820, 2021).
cleft lip (1 paper, 2017). Congenital defect in the upper lip where the maxillary prominence fails to merge with the merged medial nasal prominences. "The fact that Rdh10 mutants exhibit either a midfacial cleft or cleft lip in combination with CA suggests that retinoid signaling mediated by Rdh10 may contribute to the etiology of facial clefts in association with CA." (PMID 28169399, 2017).
cleft palate (1 paper, 2021). Cleft palate is a fissure type embryopathy that affects the soft and hard palate to varying degrees. "Additionally, probability of dysphagia was also identified in Rdh10 mutant mice with cleft palate due to retinoid deficiency, TPH2 knockout (TPH-/-) mice with serotonin (5-hydroxytryptamine [5-HT]) deficiency, and Uch-L1gad/Uch-L3Δ3–7 double homozygous mice used as a neuro-degenerative animal model." (PMID 34067192, 2021). "Dysphagia demonstrated as fetal mouth movement defects correlated with cleft palate in Rdh10 was confirmed through X-ray microtomography, in utero ultrasound video, ex vivo culture, and tissue staining." (PMID 34067192, 2021).
endometriosis (1 paper, 2026). The growth of functional endometrial tissue in anatomic sites outside the uterine body. "Similarly, in JAR cells co-cultured with gestational epithelial endometriosis, NR2F2 and IGF2 were upregulated, whereas MDFI, SP3, and RDH10 were downregulated." (PMID 42282918, 2026).
glomerulonephritis (1 paper, 2024). A renal disorder characterized by damage in the glomeruli. "In contrast, PEC-A1 had little Aldh1a2, Rdh10, Stra6 and Rbp1 expression in control mice and on day 1 of anti-GBM glomerulonephritis but had higher Rdh10 mRNA expression on day-5 compared to day-1 in anti-GBM glomerulonephritis." (PMID 39360029, 2024).
ischemic stroke (1 paper, 2024). A stroke disorder caused by obstruction of blood flow to the brain, due to thrombotic (local blood clot formation) or embolic (due to a blood clot or other material traveling from another site) event. "Rdh10 upregulation by pericytes after ischemic stroke might implicate a role for the pericytes in neuroprotection events." (PMID 37378751, 2024).
microcephaly (1 paper, 2026). A congenital or acquired developmental disorder in which the circumference of the head is smaller than normal for the person's age and sex. "Reduced levels of ECM-related proteins, such as RDH10 and RARA, linked to microcephaly, indicate that ECM dysregulation may contribute to the structural brain abnormalities reported in ALG13-CDG." (PMID 41597222, 2026).
Obesity (1 paper, 2021). Accumulation of substantial excess body fat. "We have reported that eliminating one Rdh10 copy in vivo (Rdh10+/−) reduced RA modestly in adult liver and white adipose (≤25%) and increased diet-induced obesity in both sexes." (PMID 34419449, 2021).
tumor (10 papers, 2015 to 2025). "As expected, Rdh10-deficient memory OT-I cells suppressed the tumor growth greater than control memory OT-I cells, resulting in prolonged survival." (PMID 35844620, 2022). "The properties of Rdh10-deficient memory T cells suggest Rdh10 as a potential target to improve an effect of cancer immunotherapy because TCM has been shown to have a great anti-tumor activity." (PMID 35844620, 2022). "ID3, RDH10 and EOMES are transcription factors associated with a dysfunctional tumor-infiltrating T cell state." (PMID 36135194, 2022). "In vivo, RDH10 suppression significantly reduced xenograft tumor growth." (PMID 29285249, 2017). "Furthermore, both tumor weight and fluorescence density were significantly lower in the RDH10-shRNA group than in the control Scr-shRNA group (n=10, P=0.0017 and 0.011, respectively)." (PMID 29285249, 2017). "The negative correlation between the methylation status of DHRS3, LRAT, and RDH10 and their gene expression levels suggests that methylation changes could regulate the expression of key genes involved in RA metabolism, possibly altering tumor behavior." (PMID 40535799, 2025).